GAB1 (GRB2 associated binding protein 1)
Diseases named in the same sentence as GAB1 in open-access papers (continued):
Sharing a sentence is not in itself a finding about the gene and the disease.
hilar cholangiocarcinoma (continued). "In summary, experimental results demonstrate that VEGFR-2, Gab1 and MMP-9 are closely correlated with hilar cholangiocarcinoma and that Gab1 or VEGFR-2 up-regulates growth and invasion and down-regulates apoptosis in ICBD-1 cells via the PI3K/Akt pathway." (PMID 24312291, 2013). "Relationship between VEGFR-2, Gab1 and MMP-9 expression in hilar cholangiocarcinoma tissues and patient clinical and pathological parameters." (PMID 24312291, 2013). "In this study, immunohistochemistry was first used to detect and analyze the expression of Gab1, VEGFR-2, and MMP-9 in hilar cholangiocarcinoma solid tumors and the relationships to the clinical pathological features." (PMID 24312291, 2013). "Gab1, VEGFR-2, and MMP-9 were highly expressed and positively correlated with each other in hilar cholangiocarcinoma tissues, which were related to lymph node metastasis and differentiation." (PMID 24312291, 2013). "In this study, we detected VEGFR-2, Gab1 and MMP-9 expression in solid tumor hilar cholangiocarcinoma tissues to study their interactions and relationships with the clinical and pathological characteristics of hilar cholangiocarcinoma." (PMID 24312291, 2013). "This the first study to describe correlations between Gab1 and hilar cholangiocarcinoma and to provide preliminary exploration of the biological role of the VEGFR-2/Gab1/PI3K/Akt pathway." (PMID 24312291, 2013). "Because our results showed a positive relationship among VEGFR-2, Gab1 and MMP-9 in hilar cholangiocarcinoma, we proposed that the VEGFR-2/Gab1/PI3K/Akt signaling pathway was likely present in hilar cholangiocarcinoma and could influence MMP-9 expression." (PMID 24312291, 2013). "Furthermore, Gab1 and VEGFR-2 siRNA were used to interfere the hilar cholangiocarcinoma cell line ICBD-1 and then detect the PI3K/Akt signaling pathway, MMP-9 levels and malignant biological behaviors of tumor cells." (PMID 24312291, 2013). "We presumed that VEGFR-2, Gab1 and MMP-9 likely play roles in hilar cholangiocarcinoma." (PMID 24312291, 2013). "A preliminary study of the mechanisms involved indicates that the VEGFR-2/Gab1/PI3K/Akt signaling pathway participates in regulating the malignant biological behaviors (e.g., growth, apoptosis and invasion) of hilar cholangiocarcinoma via the PI3K/Akt signaling pathway." (PMID 24312291, 2013). "Because the VEGFR-2/Gab1/PI3K/Akt signaling pathway promotes cell growth and invasion and MMP-9 is one important downstream target protein of PI3K/Akt, we presumed that they may play roles in hilar cholangiocarcinoma." (PMID 24312291, 2013). "VEGFR-2 was reported an upstream protein of Gab1 in endothelial cells and our data showed that VEGFR-2 and Gab1 were positively correlated in hilar cholangiocarcinoma, so we detected whether VEGFR-2 was the upstream protein of Gab1 in hilar cholangiocarcinoma cells." (PMID 24312291, 2013).
liver disease (4 papers, 2011 to 2024). "As the level of Gab1 activation by cMet and TGF-β can exhibit contradictory functions depending on the stage of liver disease progression, more detailed studies on Gab1 expression are required for a clear understanding of its functional characteristics." (PMID 38935609, 2024). "In this report, we demonstrate that hepatocyte Gab1 expression is regulated during different stages of liver disease progression and Gab1 expression is inversely related to TGF-β expression." (PMID 38935609, 2024). "Notably, Gab1 level is decreased in the early stage of liver disease with the increased level of TGF-β, while opposite results were observed in the liver fibrosis model." (PMID 38935609, 2024). "Based on our findings and previous reports, it is likely that cross-regulation of TGF-β and Gab1 signaling may play a role in the regulation of liver diseases." (PMID 38935609, 2024). "However, the relationship between Gab1 expression and the outcome of liver diseases is still unclear." (PMID 38935609, 2024). "Based on these results, we have formulated a hypothesis that Gab1 may have a role in regulating the severity of liver disease progression by interacting with the TGF-β signaling pathway." (PMID 38935609, 2024). "Our results indicate that the effect of Gab1 and TGF-β on the ERK pathway is dependent on the stage of liver disease progression." (PMID 38935609, 2024). "Accordingly, in the early stages of liver disease, the TGF-β signaling pathway in hepatocytes is enhanced while Gab1(Y627) activation is decreased." (PMID 38935609, 2024).
meningioma (4 papers, 2019 to 2024). A generally slow growing tumor attached to the dura mater. "GAB1 has emerged as a significant biomarker, detectable through immunohistochemistry and useful in excluding HH-independent meningiomas." (PMID 39568072, 2024). "We found that meningiomas with predicted Hh signaling activating events (including recurrent SMO variants and structural events on 2q or 7q) exhibited robust staining of GAB1, a common clinical marker used to identify Hh pathway activation." (PMID 37805627, 2023). "By contrast, no GAB1 staining was observed in meningiomas with non-Hh drivers." (PMID 37805627, 2023).
psoriasis (4 papers, 2020 to 2025). An autoimmune condition characterized by red, well-delineated plaques with silvery scales that are usually on the extensor surfaces and scalp. "The underlying mechanism related to miR-183-3p/GAB1 axis-mediated psoriasis needs further investigations." (PMID 32650835, 2020). "Thematic mapping recovered basic themes (psoriasis, keratinocytes, inflammation), motor themes (miR-146a-5p, exosomes, GAB1), and emerging terms (STAT3, adalimumab)." (PMID 41458345, 2025). "Subsequently, circ_0061012/miR-194-5p/GAB1 signal axis was identified to be involved in the pathogenesis of psoriasis." (PMID 33393621, 2021). "GAB1 expression was aberrantly up-regulated in lesional skin tissues of psoriasis patients and IL-22-induced HaCaT cells compared with that in healthy skin tissues and un-treated HaCaT cells." (PMID 33393621, 2021). "In conclusion, circ_0061012 contributed to IL-22-induced proliferation and motility of HaCaT cells through targeting miR-194-5p/GAB1 axis, providing a novel insight into developing new therapeutic targets for psoriasis patients." (PMID 33393621, 2021). "We concluded that circ_0061012 elevated the expression of Ki67 and MMP9 to promote psoriasis progression through targeting miR-194-5p/GAB1 axis." (PMID 33393621, 2021). "Circ_0061012 accelerated IL-22-induced proliferation and metastasis in HaCaT cells through enhancing GAB1 expression via sponging miR-194-5p in psoriasis." (PMID 33393621, 2021). "MiR-194-5p and GAB1 plasmid were co-transfected into IL-22-induced HaCaT cells to explore if miR-194-5p suppressed psoriasis progression via targeting and suppressing GAB1." (PMID 33393621, 2021). "GAB1 mRNA level was prominently enhanced in skin tissues of psoriasis patients when compared with healthy volunteers." (PMID 33393621, 2021). "The top five major signalling pathways in the psoriasis blood dryness group included interferon signaling, GAB1 signalosome, negative regulators of DDX58/IFIH1 signaling, negative regulation of binding, ubiquinone and other terpenoid-quinone biosynthesis." (PMID 35126107, 2021). "MiR-183-3p exhibited inhibition property in the proliferation and migration of HaCaT cells via down-regulation of GAB1, suggesting the potential therapeutic strategy for psoriasis." (PMID 32650835, 2020). "GAB1 was observed to regulate the migration ability of keratinocytes, implying GAB1 might exert essential role in psoriasis progression." (PMID 33393621, 2021). "We discovered the potential mechanism behind the role of GAB1 in psoriasis." (PMID 33393621, 2021). "This is the first study identifing GAB1 as a binding target of miR-183-3p during psoriasis." (PMID 32650835, 2020). "Recently, GAB1 was shown to be aberrantly expressed in multiple sclerosis and psoriasis." (PMID 32650835, 2020). "Moreover, GAB1 was found to be involved in the migration of keratinocyte, as well as wound healing, suggesting its potential role in the pathogenesis of psoriasis." (PMID 32650835, 2020). "In addition, miR-183-3p could repress the mRNA and protein expression of GAB1, suggesting that miR-183-3p could suppress the proliferation and migration of keratinocyte in psoriasis by inhibiting GAB1." (PMID 32650835, 2020).
cognitive deficits (3 papers, 2023 to 2025). "Further mechanic study found that METTL3-mediated m6A modification on pri-miR-221 promoted its processing and maturation that subsequently upregulated miR-221-3p expression to inhibit GRB2-associated binding protein 1 (Gab1) expression, which worsened the cognitive deficits in MDD rats." (PMID 37189411, 2023). "Gab1 is also an adaptor protein with phospho-site-mediated coupling to SHP2 upstream of excitatory neuronal ERK activation and synaptic plasticity; it is implicated in cognitive deficits in AD." (PMID 38542311, 2024).
colitis (3 papers, 2019 to 2023). Inflammation of the colon. "Taken together, these results indicate that epithelial Gab1 deficiency facilitates inflammatory cell infiltration and aggravates colonic inflammation in a colitis microenvironment." (PMID 36795486, 2023). "Consistently, administration of RIPK3 inhibitor showed significant alleviation of colitis in Gab1-deficient mice." (PMID 36795486, 2023). "Deletion of Gab1 in epithelial cells rendered mice susceptible to dextran sodium sulfate–induced (DSS-induced) colitis by perpetuating RIPK3-dependent necroptosis." (PMID 36795486, 2023). "The aggravated colitis due to epithelial Gab1 deficiency was significantly rescued by GSK’872 administration, as exemplified by DSS-induced macroscopic changes (body weight loss, diarrhea, and rectal bleeding) being significantly alleviated." (PMID 36795486, 2023). "The aggravated colitis due to epithelial Gab1 deficiency was rescued by IFX administration, as exemplified by significantly improved macroscopic changes, colon length, as well as intestinal epithelial integrity." (PMID 36795486, 2023). "RIPK3 inhibition alleviates colitis in epithelial Gab1-deficient mice." (PMID 36795486, 2023). "Epithelial Gab1 deficiency renders mice susceptible to DSS-induced colitis." (PMID 36795486, 2023). "Notably, epithelial Gab1-deficient mice manifested exacerbated experimental colitis upon DSS treatment." (PMID 36795486, 2023). "Moreover, pharmacological inhibition of RIPK3 substantially alleviated experimental colitis with reduced inflammation in Gab1IEC -KO mice, suggesting that hyperactivation of RIPK3 and necroptosis largely contributes to exacerbated colitis in epithelial Gab1-deficient mice." (PMID 36795486, 2023). "To unravel the in vivo role of epithelial Gab1 in colitis, we first generated intestinal epithelium–specific Gab1-knockout (Gab1IEC-KO) mice." (PMID 36795486, 2023). "We have shown that Gab1 ablation in IECs contributed to the aggravated colitis due to excessive RIPK3-dependent necroptosis." (PMID 36795486, 2023). "Single-cell RNA-Seq analysis of patients with UC, as well as a colitis mouse model, further identified that Gab1 is predominantly decreased in IECs, suggesting the probable role of epithelial Gab1 in disease progression." (PMID 36795486, 2023). "Further GO analysis underscored an enrichment of gene sets responsible for programmed cell death in the colonic transcriptome of Gab1IEC-KO mice, implicating the potential cellular process Gab1 involved during colitis development." (PMID 36795486, 2023). "Together, these data suggest that IEC necroptosis triggered by Gab1 deficiency aggravates intestinal barrier dysfunction and bowel inflammation in DSS-induced colitis." (PMID 36795486, 2023). "In this study, we demonstrated that Gab1 expression was strikingly decreased in patients with IBD as well as in a mouse colitis model." (PMID 36795486, 2023). "Consistent with the observations in human UC, we found that the reduction of Gab1 expression in colonic tissues was significantly rescued after anti-TNF treatment in the DSS-induced colitis model." (PMID 36795486, 2023). "Future studies that target Gab1 in combination with Gab2/3 may shed light on the combined role of all Gabs in regulation of immune cell activation and colitis development." (PMID 30936879, 2019). "Another recent study supports the involvement of necroptosis in DSS-induced colitis, since the authors showed that GAB1 is involved in RIPK3 dephosphorylation and inhibition of IEC necroptosis using a DSS colitis model." (PMID 37409125, 2023). "Taken together, these findings define a predominant role of Gab1 in IECs, rather than in myeloid cells, in protecting mice from DSS-induced colitis." (PMID 36795486, 2023).
deafness (3 papers, 2021 to 2024). An inherited or acquired condition characterized by the complete loss of the ability to hear from one or both ears. "MAP3K1 phosphorylates serine and threonine and functions in a signaling pathway where pathogenic variants of HGF, MET, and GAB1 were previously reported to be associated with human deafness DFNB39, DFNB97, and DFNB26, respectively." (PMID 39062623, 2024). "Genes already associated with hearing or deafness (mouse and/or zebrafish) were selected as controls/references for comparison and validation of the candidate genes’ results: Eya4 (DFNA10), Gsdmea (DFNA5), Gsdmeb (DFNA5), Pou4f1, Elavl4, Sclla3a, Gab1 (DFNB26), and Mettl1 (DFNM)." (PMID 36553541, 2022). "By analogy with DNFM1/METTL13, which acts as a dominant suppressor of recessive DFNB26/GAB1 deafness, it is intriguing to speculate about the existence of a dominant modifier of SLC22A4, which could suppress the onset of deafness in the non-penetrant individual from family NSHL7." (PMID 33643381, 2021).
dilated cardiomyopathy (3 papers, 2021 to 2024). Cardiomyopathy which is characterized by dilation and contractile dysfunction of the left and right ventricles. "Cardiac-specific GAB1 knock-out in mice has been reported to lead to dilated cardiomyopathy associated with mitochondrial damage and cardiomyocyte apoptosis." (PMID 38969939, 2024). "The other 2 (KY and GAB1) encode proteins involved in normal cell growth responses; in mice, GAB1 gene ablation causes a dilated cardiomyopathy and mitochondrial damage." (PMID 37606047, 2023). "Among them, some pathways could be explained reasonably, such as dilated cardiomyopathy, hormone ligand binding receptors, GAB1 signalosome, platelet aggregation plug formation and so on." (PMID 34586716, 2021).
idiopathic pulmonary fibrosis (3 papers, 2019 to 2021). Idiopathic pulmonary fibrosis (IPF) is a nonneoplastic pulmonary disease that is characterized by the formation of scar tissue within the lungs in the absence of any known cause. "Moreover, deficiency of either Gab1 or Gab2 can meliorate BLM-induced pulmonary fibrosis by destroying M2 macrophage polarization." (PMID 33637697, 2021). "A positive role for Gab1/2 in M2 macrophage polarization and idiopathic pulmonary fibrosis has been described." (PMID 30936879, 2019).
liver fibrosis (3 papers, 2020 to 2024). "Loss of Gab1 aggravates liver fibrosis in the mouse model, while Gab1 contributes to the prevention of liver fibrogenesis." (PMID 38935609, 2024). "Ron and Met primarily signal through the large adaptor protein, Gab1 and loss of Gab1 has been shown to aggravate experimental liver fibrosis in mice." (PMID 32796650, 2020). "To test this, we determined a pathologic role of Gab1 in the progression of liver fibrosis in vivo using the established murine model of liver fibrosis induced by CCL4 treatment." (PMID 38935609, 2024). "We conducted the in vivo study using the carbon tetrachloride (CCL4)-induced liver fibrosis mouse model to clarify the changes in Gab1 expression in chronic liver disease." (PMID 38935609, 2024). "In the present study, we described the role of Gab1 in the development of liver fibrosis via HGF/c-Met signaling axis." (PMID 38935609, 2024). "One interesting question raised by present work is how Gab1 is involved in the progression of liver fibrosis." (PMID 38935609, 2024). "Our findings suggest a role for Gab1 in the development of liver fibrosis." (PMID 38935609, 2024). "Given the role of TGF-β in severe chronic liver disease, and the relation of Gab1 to TGF-β production, we hypothesize that Gab1 may play a role in regulation of liver fibrosis development." (PMID 38935609, 2024). "However, a contradictory role of Gab1 has been reported for exerting protective effect in liver fibrosis." (PMID 38935609, 2024). "In addition, knockdown of Gab1, an important protein in the receptor tyrosine kinase pathway, significantly exacerbated liver fibrosis in animal models." (PMID 34434654, 2021). "Thus, it is important to clarify the role of Gab1 in the progression of liver fibrosis." (PMID 38935609, 2024). "Surprisingly, Gab1 mRNA and relative protein levels are significantly increased in CCL4-induced liver fibrosis mice compared to those in control mice." (PMID 38935609, 2024). "Thus, Gab1 may affect HGF/c-Met signaling and trigger cell proliferation during liver fibrosis." (PMID 38935609, 2024).
pancreatic ductal adenocarcinoma (3 papers, 2023 to 2024). An infiltrating adenocarcinoma that arises from the epithelial cells of the pancreas. "Insulin involvement in immune checkpoint regulation enhances PD-L1 expression in pancreatic ductal adenocarcinoma cells via many routes in the three cell lines studied, including increased InsR-A expression in A818-6 cells and modification of the adaptor protein Gab1 in BxPc3 cells." (PMID 37664033, 2023). "Insulin involvement in immune checkpoint regulation boosts PD-L1 expression in pancreatic ductal adenocarcinoma cells through a variety of pathways in the three cell lines studied, including increased InsR-A expression in A818-6 cells and modification of the adaptor protein Gab1 in BxPc3 cells." (PMID 37377916, 2023).
prostate carcinoma (3 papers, 2016 to 2020). A carcinoma that arises from epithelial cells of the prostate gland. "In our previous work, we showed that dissociation of the PAR complex promotes prostate cancer metastasis and that interaction of Gab1 with Par3 and Par1b can induce dissociation of the PAR complex in epithelial cells." (PMID 30665442, 2019). "For instance, β1 expression regulates type 1 insulin-like growth factor receptor (IGF-IR) via Grb2-associated binder-1 (Gab1), which is responsible for the inhibition of phosphorylation of IGF-IR, leading to anchorage-independent growth of prostate cancer." (PMID 27929432, 2016).
triple-negative breast carcinoma (3 papers, 2015 to 2024). An invasive breast carcinoma which is negative for expression of estrogen receptor (ER), progesterone receptor (PR), and human epidermal growth factor receptor 2 (HER2). "This represents a groundbreaking discovery in targeting GAB1 signaling which may be used for cancer therapy, especially for triple negative breast cancer patients." (PMID 25569504, 2015). "Our results also showed that the triple-negative breast cancer cell line, MDA-MB-231, was more resistant to GAB1 inhibitors than ER-positive breast cancer cell line, T47D." (PMID 25569504, 2015).